ZNF385C (zinc finger protein 385C)
Gene: Protein-coding gene on chromosome 17 (42,025,576 to 42,098,479, reverse strand). Ensembl gene ENSG00000187595.
Subcellular location: Nucleus
Genetic constraint (gnomAD): Loss-of-function variants: 23 observed, 32.31 expected, observed/expected ratio (o/e) 0.71, 90% interval 0.51 to 1.01. The upper end of that interval is the gene's LOEUF score, 1.01, which puts it in group 4 of 6, group 1 being the genes least tolerant of losing a copy. Missense variants: 526 observed, 544.23 expected, observed/expected ratio (o/e) 0.97, 90% interval 0.9 to 1.04. Synonymous variants: 211 observed, 223.84 expected, observed/expected ratio (o/e) 0.94, 90% interval 0.84 to 1.06.
Homologues: Orthologues: chimpanzee ZNF385C (98% identical), macaque ZNF385C (93% identical), rabbit ZNF385C (90% identical), pig ZNF385C (89% identical), rat Zfp385c (83% identical), mouse Zfp385c (70% identical), guinea pig ZNF385C (60% identical), tropical clawed frog znf385c (42% identical), zebrafish znf385c (40% identical), Drosophila melanogaster dbf (19% identical), Drosophila melanogaster CG1231 (14% identical). Paralogues in human: ZNF385B (39% identical), ZNF385D (34% identical), ZNF385A (29% identical), ZMAT1 (13% identical), ZMAT3 (13% identical), ZMAT4 (11% identical), ZNF346 (11% identical), ZMAT2 (8% identical), KRCC1 (4% identical).
Diseases named in the same sentence as ZNF385C in open-access papers:
ZNF385C is named in the same sentence as 3 diseases in open-access papers, as found by Europe PMC text mining. Sharing a sentence is not in itself a finding about the gene and the disease. The quoted sentences say what the papers report.
leukemia (1 paper, 2025). A malignant (clonal) hematologic disorder, involving hematopoietic stem cells and characterized by the presence of primitive or atypical myeloid or lymphoid cells in the bone marrow and the blood.
cancer (1 paper, 2023). A tumor composed of atypical neoplastic, often pleomorphic cells that invade other tissues. "Two other genes, ZNF385C and PRAME, were previously reported to be overexpressed in specific cancer types but with largely unknown molecular functions." (PMID 36982699, 2023).
ZNF385C also shares sentences with these, for which no sentence is quoted: tumor (1 paper).